INS (insulin)
Diseases named in the same sentence as INS in open-access papers (continued):
Sharing a sentence is not in itself a finding about the gene and the disease.
Hepatic steatosis (continued). "However, the hepatic steatosis was not caused by loss of GR in Kupffer cells themselves, as GRClec4fCre, compared to GRLysMCre mice, did not develop aggravated steatosis or changes in whole-body insulin and glucose tolerance." (PMID 37080971, 2023). "Given the results from insulin-treated and PHZ-treated mice, it was suggested that insulin signaling has certain protective effects against the development of HCC as well as hepatic steatosis and fibrosis, besides its glucose-lowering effects." (PMID 37852976, 2023). "PCOS adolescents with hepatic steatosis presented with higher BMI and abdominal adiposity, higher SBP, worse insulin sensitivity, and worse hyperandrogenism than PCOS adolescents without steatosis." (PMID 36675485, 2023). "The jaboticaba extract treatments reduced weight gain and adiposity, improved insulin sensitivity, increased HDL cholesterol, and prevented hepatic steatosis." (PMID 38138571, 2023). "In rodents the reversal of hepatic steatosis is accompanied by reduced hepatic DAG levels and improved insulin action, whereas total hepatic ceramide levels were unchanged." (PMID 37059417, 2023). "This deteriorated adipose tissue function contributes to impaired hepatic insulin sensitivity (as demonstrated by decreased IRS1 expression) and pronounced hepatic steatosis (as evident by abundant lipid droplets and higher liver weight)." (PMID 37520561, 2023). "Fatty liver disease is another frequent condition in subjects with FPLD2, mainly due to inadequate adipose storage and ectopic fat accumulation that impairs insulin signalling and other cellular functions." (PMID 36899861, 2023). "Further, more clarity is needed to define the structural changes in the IR in an insulin-resistant state and to determine if activation of the insulin receptor is necessary for lipogenesis in NAFLD after the onset of fatty liver disease." (PMID 37242206, 2023). "The pathological mechanisms of fatty liver in chickens are similar to nonalcoholic fatty liver disease (NAFLD), including insulin resistance, inflammation, and liver oxidative stress." (PMID 35889001, 2022). "Albeit retaining an insulin‐sensitive state, HFD‐fed Il1r1Hep−/– mice developed macrovesicular hepatic steatosis." (PMID 36101976, 2022). "In an insulin-resistant state, the augmentation of both hepatic FA uptake (65%) and DNL (25%) contributes to hepatic steatosis in human NAFLD." (PMID 34855620, 2022). "Similar trends for insulin and HOMA-IR were also observed for the proportions of hepatic steatosis (HS) in both men and women." (PMID 36160146, 2022). "We found that KPA treatment in insulin-resistant wild-type C57BL/6J mice and DIAMOND mice reduced hepatic steatosis, decreased liver enzyme ALT, and reduced serum TGs, FFA, and cholesterol." (PMID 35349482, 2022). "Experimental data showed that fasting insulin levels (p<0.001), AST (P=0.042) and ALT (P=0.005) in the group with non-alcoholic fatty liver were significantly higher than the non-alcoholic group." (PMID 35974947, 2022). "Participants in G4 group develped the highest BMI, WC, BP, LDL, insulin, HOMA-IR, HbA1c, and fatty liver." (PMID 35165286, 2022). "Based on a series of these results in genetically modified mouse models of insulin signaling, hepatic insulin signaling via at least the IR/Irs/PI3K/Akt pathway is definitely important for the development of fatty liver." (PMID 33923817, 2021). "Hepatic steatosis is a driving force for NAFLD because increased intracellular TG accumulation induces inflammation, oxidative stress and insulin resistance by generating lipotoxic intermediates, which leads to NASH, fibrosis and cirrhosis." (PMID 34681759, 2021). "FGF21 reverses liver steatosis by acting on hepatic lipid metabolism and glucose uptake, inducing thermogenesis in BAT and WAT, improving insulin sensitivity in muscles and liver, and increasing glucose uptake by adipose tissues." (PMID 34943946, 2021).
Hepatic steatosis (continued). "In the present study of 88 overweight/obese Chinese adults, we found that increased tertiles of serum FT3 were significantly associated with higher levels of BMI, waist circumference, WHtR, fasting insulin, HOMA-IR, and hepatic steatosis (CAP and FLI)." (PMID 34794374, 2021). "In addition, BJ treatment effectively alleviated hepatic steatosis and mitochondrial dysfunction observed in the prediabetic animals, as suggested by the amelioration of bioenergetics parameters and key targets of inflammation, insulin signaling, ketogenesis, and fatty acids oxidation." (PMID 34959746, 2021). "Our results show that NQO1 overexpression leads to improvements in insulin sensitivity and in glucose, lipid and NAD+ metabolism while providing protection from HFD-induced liver steatosis and macrophage infiltration in the adipose tissue." (PMID 33298924, 2020). "PHHs in spheroids remain differentiated for at least 3 to 4 weeks, and hepatic steatosis can be induced by supplementing the culture medium with pathophysiological concentrations of FFA, carbohydrates and insulin." (PMID 33374435, 2020). "In summary, we find a novel insight that ascorbate prevents hepatic steatosis by inhibiting SOCS3 and improving insulin sensitivity in vitro and in vivo." (PMID 32158492, 2020). "Treatment with a functionally liver-targeted mitochondrial uncoupler protected the aged L-Mttp−/− mice against the development of hepatic steatosis, increased plasma membrane sn-1,2-DAG content, PKCε activation, and hepatic insulin resistance." (PMID 32907986, 2020). "SOCS3 is a repressor of insulin signaling pathway and it has been reported that inhibition of SOCS3 ameliorated hepatic steatosis and hypertriglyceridemia." (PMID 32158492, 2020). "Liver steatosis is the first step in the pathogenesis of NAFLD/NASH, as it can lead to sustained hepatic inflammation through hepatocyte insulin resistance, ER stress, and progressive cellular dysfunction." (PMID 33271781, 2020). "Interestingly, in addition to the strong advantage of using the oral route, this approach is at least as efficient as the current marketed drug as a comparison and could even be more potent for improving oral glucose tolerance, insulin resistance and hepatic steatosis." (PMID 31401561, 2020). "Consistent with these improvements in hepatic steatosis and in glucose tolerance, CRMP treatment markedly increased both whole-body insulin responsiveness and hepatic insulin sensitivity." (PMID 32907986, 2020). "Here we suggest that this vicious cycle can be reversed through antagonizing ERRα activity given that inhibition of ERRα decreases blood insulin levels, increases insulin sensitivity and protects animals from HFD-induced fatty liver." (PMID 31024446, 2019). "Our paper analyzed the effects of serum insulin and HOMA-IR on liver steatosis, HBV DNA levels, and liver elasticity." (PMID 31807383, 2019). "Hepatic steatosis in NAFLD may be caused by several processes, including an increased influx of free fatty acids stemming from overnutrition, increased hepatic de novo lipogenesis, increased insulin resistance, reduced fat oxidation, and decreased secretion of very low-density lipoprotein." (PMID 31083413, 2019). "However, given the fact that overexpression of ChREBP also causes hepatic steatosis, which impairs the insulin sensitivity, thus activation of ChREBP may be not a good choice for the improvement of hepatic insulin sensitivity." (PMID 31623194, 2019). "Chronic alcohol-induced increased ghrelin impairs insulin secretion, therefore, stimulates FFA release from adipose tissue, resulting in the promotion of hepatic de novo lipogenesis and development of fatty liver." (PMID 31546643, 2019). "In obese mice, administration of recombinant FGF21 has been shown to alleviate hepatic steatosis, induce browning of WAT, increase energy expenditure, improve insulin sensitivity, and restore glucose tolerance." (PMID 31736870, 2019).
Hepatic steatosis (continued). "Specifically, dutasteride exacerbated the weight gain, increased the fasting insulin and insulin response to a GTT, and induced hepatic steatosis in mice fed a high-fat diet." (PMID 31199473, 2019). "Although some studies have reported that SIRT1 inhibition in the liver can contribute to hepatic steatosis, there is some evidence that SIRT1 inhibition in the liver or adipocytes can enhance insulin sensitivity in animals exposed to a high-fat diet." (PMID 31683679, 2019). "3,5-T2 treatment was shown to prevent or treat hepatic steatosis and obesity induced by HFD, increasing insulin sensitivity in rats." (PMID 30072951, 2018). "P465L mice showed increased levels of insulin and free fatty acids (FFA) as well as increased liver steatosis." (PMID 29790245, 2018). "BBR treatment improves NEFA-impaired mitochondrial respiratory chain function and insulin signaling by increasing PGC-1α expression in hepatocytes, which provides a potential new strategy for the prevention and treatment of fatty liver in dairy cows." (PMID 29882814, 2018). "Mechanisms that induce fatty liver disease are mostly due to increased NEFA delivery from peripheral WAT and a greater de novo lipogenesis alongside with insulin resistance, whereas β-oxidation of FA seems to be of marginal importance." (PMID 30374109, 2018). "But fasting serum C-peptide levels, glucose-to-insulin ratio, insulin-to-C-peptide ratio or HOMA–IR values were comparable among the groups at this time point, suggesting that IR is a consequence of the onset of hepatic steatosis." (PMID 28134848, 2017). "When analyzing the biochemical data, we found that Insulin, HOMA-IR-index, ALT, AST, γ-GT, Triglyceride levels were significantly higher, and HDL-C levels were significantly lower in liver steatosis children than controls." (PMID 28759573, 2017). "The insulin-sensitizer agonist, PPAR-γ, stimulates adiponectin production, which in turn decreases hepatic steatosis by activating AMP-activated protein kinase, enhancing insulin sensitivity." (PMID 28134848, 2017). "At molecular level, insulin signalling impairment and decreased activation of AMPK are consistent with hepatic steatosis, inflammation and increase in ROS production." (PMID 28628674, 2017). "Intriguingly, however, TN-HFD-IF mice still exhibited a mild improvement in glucose tolerance, insulin sensitivity, and HOMA-IR, with a reduction in body weight, fat mass, as well as hepatic steatosis, compared to TN-HFD-AL mice." (PMID 29039412, 2017). "Emphasizing on its capacity in remodeling insulin signaling and mitochondrial fitness, we examined the efficacy of TM5441 in decreasing hepatic steatosis, inflammation, and ultimately fibrosis, which are the hallmarks of NAFLD progression." (PMID 29163785, 2017). "In the case of hyperinsulinemia, insulin continues to drive lipogenesis via the SREBP1 pathway in addition to failing to suppress gluconeogenesis, contributing to exacerbating hepatic steatosis." (PMID 29057834, 2017). "It was demonstrated that GRP78 expression inhibits insulin- and ER stress-induced SREBP-1c activation and reduces hepatic steatosis in mice." (PMID 27336443, 2016). "In addition, insulin pretreatment could exert a significant protective effect on oxidative damage and inflammatory reaction in the liver against ethanol exposure, but insulin can also exacerbate hepatic steatosis in mice exposed to ethanol." (PMID 26798419, 2016). "The reduced liver steatosis in Arg-II−/− mice on HFD is in line with the results of our previous study showing an improved glucose tolerance and insulin sensitivity in these mice." (PMID 26846206, 2016). "Indeed the expression of SREBP-1c can be regulated upwards by the administration of insulin and ethanol, suggesting that SREBP-1c activation might contribute to the deteriorative effects of insulin preadministration on hepatic steatosis in mice exposed to ethanol." (PMID 26798419, 2016).
Hepatic steatosis (continued). "Moro orange juice hindered weight gain, enhanced insulin sensitivity (as determined by an insulin tolerance test), decreased TAG (triacylglycerols), TC (total cholesterol), hepatic steatosis and hepatic TAG content." (PMID 27367676, 2016). "The findings lead to introduction of an informative biomarker panel including INS, PPARA, LEP, SREBF1, and ALB proteins related to the fatty liver disease." (PMID 28224024, 2016). "In many models of hepatic steatosis, diacylglycerol mediated activation of PKC impairs hepatic insulin signaling." (PMID 26485433, 2015). "Moreover, it is very likely that the systemic enhancement in insulin sensitivity, with increased Akt activity in muscle and adipose tissue in addition to the liver, leads to an overall improved metabolism of C2βD1212A/D1212A mice, which reduces the development of hepatic steatosis as a consequence." (PMID 26655903, 2015). "Voluntary exercise also decreases oxidative stress, hepatic steatosis and JNK activation, all of which contribute to suppressing chronic low-level inflammation in the liver and improve systemic insulin resistance." (PMID 26172834, 2015). "Pioglitazone improves hepatic steatosis in the rats with HFD-induced NASH and upregulates ACE2 expression in insulin-sensitive tissues." (PMID 24558317, 2014). "The purpose of this study was to test the accuracy of NAFLD liver fat score (NAFLD-LFS), hepatic steatosis index (HSI) and fatty liver index (FLI) against 1H-MRS and their relationships with insulin sensitivity and secretion." (PMID 24732091, 2014). "In conclusion, pioglitazone, one of TZDs, improves hepatic steatosis in the rats with HFD-induced NASH and upregulates ACE2 expression in insulin-sensitive tissues." (PMID 24558317, 2014). "The suppression of insulin-signaling pathways leads to the uncontrolled activation of hepatic SREBP1 c, which in turn results in fatty liver." (PMID 25101998, 2014). "In summary, the research to date has shown that despite women of African ancestry being more insulin resistant than their white counterparts, they have less VAT and hepatic steatosis and more peripheral SAT." (PMID 23401754, 2013). "The potential role of liver FA composition, insulin secretion and sensitivity, adipokine, and inflammatory responses are discussed as potential mechanisms behind CLA-induced hepatic steatosis." (PMID 21869929, 2012). "Thus, while both HFat and HFru diets are capable of causing hepatic steatosis, the mechanisms of associated hepatic insulin resistance may not be necessarily the same at the molecular level." (PMID 22355328, 2012). "Recent studies showed that weight loss could decrease hepatic steatosis and insulin sensitivity and a direct effect of GLP-1 on hepatocytes of human subjects with NASH could be mediated by activating of genes involved in fatty acid oxidation and insulin sensitivity." (PMID 22363635, 2012). "The rate of liver steatosis also shows good correlation with IRI during the OGTT, HOMA index, glucose/insulin ratio, and diastolic blood pressure." (PMID 22262974, 2012). "Treatment with silibinin improved liver steatosis and inflammation and decreased NASH-induced lipid peroxidation, plasma insulin and TNF-α." (PMID 19884114, 2011). "Animal models consistently show improved glucose tolerance, insulin sensitivity, and hepatic steatosis under fermented vs. non-fermented diets." (PMID 41599407, 2026). "Using both in vitro (LO2 cells) and in vivo (C57BL/6J mice) models, we found that PGA administration significantly attenuated body weight gain and hepatic steatosis, while reducing serum levels of TG, TC, liver transaminases (AST & ALT), and insulin resistance (p < 0.05)." (PMID 41683025, 2026). "AP also enhanced glucose tolerance and insulin sensitivity, attenuated hepatic steatosis, hepatocellular ballooning, lobular inflammation and non-alcoholic fatty liver disease (NAFLD) Activity Score, and decreased serum liver enzyme activities." (PMID 41594353, 2026).
Hepatic steatosis (continued). "In HFD-fed mice, supplementation with cheonggukjang (a short-ripened fermented soybean paste) led to significantly lower fasting glucose and insulin than HFD controls and improved hepatic steatosis, indicating anti-obesogenic effects that extend to glycemic endpoints." (PMID 41599407, 2026). "One study on mice fed a HFD as a model for hepatic steatosis reported that HCQ improves insulin sensitivity (based on HOMA-IR and HOMA-IS) without affecting β-cell function (based on HOMA-β)." (PMID 40260275, 2025). "In addition to improving insulin sensitivity and stimulating insulin secretion, MALAT1 KO also reduces hepatic steatosis and IR." (PMID 40003929, 2025). "GLP-1RAs improves a key step in the insulin signaling pathway - enhancement of PI3K/Akt pathway activity, thereby enhancing the cellular response to insulin, and they have been shown to be effective for fatty liver." (PMID 40235664, 2025). "Through integrated investigation in both 3T3-L1 adipocytes and ob/ob mice, we show that EMO co-treatment synergistically enhances RSG’s glucose-lowering and insulin-sensitizing effects while effectively mitigating RSG-induced weight gain, adipocyte hypertrophy, and hepatic steatosis." (PMID 41471299, 2025). "The citrus flavonoid nobiletin enhances insulin sensitivity and decreases hepatic steatosis without AMPK activation, instead influencing the LXR and SREBP-1c pathways to suppress hepatic lipogenesis." (PMID 40868109, 2025). "Chronic administration to diet-induced obese rats reduced hepatic steatosis, improved insulin sensitivity, decreased weight gain without affecting food intake and favorably affected dyslipidemia." (PMID 40941984, 2025). "Following 9 months of treatment, insulin levels normalized, and abdominal ultrasonography showed no signs of hepatic steatosis." (PMID 40842493, 2025). "PTEN overexpressors do not become obese when fed a high-fat diet, and unlike control siblings do not develop fatty liver disease or develop insulin sensitivity." (PMID 40636718, 2025). "These include the Fibrosis-4 index (FIB-4), MASLD Fibrosis Score (NFS), Body Mass Index-Age-Insulin Resistance Score (BAAT), Fatty Liver Index (FLI), Hepatic Steatosis Index (HSI), Zhejiang University Index (ZJU), Fatty Liver Disease Index (FLD), and Lipid Accumulation Product (LAP)." (PMID 40422919, 2025). "Liver-specific deletion of Agpat5 did not affect plasma insulin levels, glucose tolerance, plasma cholesterol levels, or hepatic steatosis in mice fed a chow diet, high-fat diet, or Western diet." (PMID 39608054, 2024). "In contrast, its conditional deletion in endothelial cells causes inflammation-driven hepatic fibrosis without adversely affecting metabolism (mice remain insulin-sensitive and do not develop hepatic steatosis)." (PMID 39640841, 2024). "In studies of hepatic steatosis, mice over-expressing DGAT2, an enzyme that catalyzes the final step of hepatic triglyceride biosynthesis, was demonstrated to develop hepatic steatosis with normal plasma glucose and insulin levels and normal insulin tolerance." (PMID 39618812, 2024). "Of note, the liver steatosis regression was also independent of changes in common parameters of cardiovascular and metabolic risks such as glycemia, insulin resistance, total and LDL cholesterol levels." (PMID 38303926, 2024). "Our data show that liver-specific deletion of Agpat5 does not impact plasma insulin levels, glucose tolerance, hepatic steatosis, or plasma lipid levels under multiple dietary conditions." (PMID 39608054, 2024). "In addition, RvE1 was found to upregulate the expression of genes involved in insulin and glucose metabolism, such as PPARγ, GLUT-4, and IRS-1, in adipose tissues and to prevent hepatic steatosis and reduce the number of macrophages in inflamed liver tissues." (PMID 39273541, 2024).